SPARC (secreted protein acidic and cysteine rich)
Diseases named in the same sentence as SPARC in open-access papers (continued):
Sharing a sentence is not in itself a finding about the gene and the disease.
tumor (continued). "In light of these evidences, it is not surprising that SPARC, a matricellular protein produced by tumor cells, promotes the expansion and recruitment of MDSCs." (PMID 32133298, 2020). "The epigenetic silencing of SPARC by methylation was then evaluated on DNA bisulfite-treated obtained from 59 surgically resected NSCLCs (19/59 non-neoplastic/tumor paired) and 11 normal lung tissues from non-neoplastic patients (NLDTs)." (PMID 32580473, 2020). "The conjugation of nanoparticles with a peptide able to specifically recognizing the SPARC protein, has made it possible to obtain an important tool that exhibited high tumor affinity with a very low binding in negative cell lines." (PMID 33050185, 2020). "The significant increase in SPARC levels was limited to the stroma and was not present in tumor cells." (PMID 31858848, 2020). "In addition, it was shown that during tumorigenesis, high SPARC expression in tumor cells promotes epithelial mesenchymal transition (EMT) and tumor aggressiveness." (PMID 32900381, 2020). "Furthermore, in the multivariate analysis it was shown, that tumor stage was the main predictor for DFS and SPARC expression just failed significance with p = 0.051." (PMID 31554208, 2019). "In addition, extracellular matrix glycoprotein (Secreted Protein, Acidic and Rich in Cysteine–SPARC), which has a high affinity for albumin and enriched in tumors, can further enhance its tumor deposition." (PMID 30621360, 2019). "In conclusion, this paper proposes SPARC as a new potential marker of MDSC, in both human and mouse, with the additional feature of controlling MDSC suppressive activity with the aim of preventing an excessive anti-tumor inflammatory state." (PMID 31281314, 2019). "Our study leverages data from plasma RNA and CTCs, published studies and focused data mining, to propose a testable model in which high concentration of PF4 induces platelet attraction into the tumor microenvironment and regulates expression and/or availability of CLU, CCL5, TGFB1, SRGN and SPARC." (PMID 31215484, 2019). "Furthermore, there was no significant impact on the 5-year DFS, but within the first year after tumor resection, a notable shift towards shorter DFS was seen for tumors with high stromal SPARC abundance (p = 0.034, Log Rank test)." (PMID 31554208, 2019). "In this subset of patients, high SPARC abundance was a predictor of survival independent of stage, therapy and tumor location." (PMID 31554208, 2019). "Further, the silencing of SPARC significantly inhibited proliferation and migration of the CRC cells, while the miR-29c-3p inhibitor promoted it, which indicated that miR-29c-3p acts as a tumor suppressor." (PMID 31757017, 2019). "We previously shown that the intracellular retention of SPARC in tumor cells through the over-expression of SCD5, an enzyme that mediated the synthesis of monounsatured fatty acids (MUFA), suppressed tumor growth through an alteration of satured and monounsatured FA balance." (PMID 31281314, 2019). "Unexpectedly, despite the influence of MDSC-derived SPARC on EMT markers and immune suppression, the tumor volume of SN25ASP tumors injected in WT and Sparc −/− mice was similar at the end, although the differed kinetics of growth that was initially faster in WT mice." (PMID 31281314, 2019). "In addition, tumor migration is upregulated by macrophage-derived cathepsins, SPARC, or CCL18, that enhance tumor cell adhesion to extracellular matrix proteins." (PMID 31684193, 2019). "In tumour specimens with adjacent omental tissues, we show that the negative correlation between both tumour and adipocyte SPARC with the nuclear localization of these factors in tumour cells and juxta-tumoral adipocytes." (PMID 30765860, 2019). "Since we observed that HSA binding to SPARC could affect its accumulation in cells in vitro, we verified the effect of SPARC on HSA accumulation in an in vivo tumor model." (PMID 31695779, 2019).
tumor (continued). "Albumin-stabilized paclitaxel nanocrystals showed enhanced uptake by SPARC+ B16F10 melanoma cells and in vivo anti-tumor efficacy, and albumin-stabilized hydroxycamptothecin nanocrystals showed enhanced intratumor accumulation and prolonged survival time in MCF-7 model tumor-bearing mice." (PMID 30621141, 2019). "The size of primary tumor did not affect the positivity of SPARC staining in tumor samples (P=0.763), but the depth of tumor invasion exhibited a significant effect on the positivity of SPARC staining (P=0.011)." (PMID 29156791, 2017). "The co-localization of SPARC and α-SMA varied greatly among the tumor tissue sections." (PMID 29156791, 2017). "Interestingly, increased mRNA expression was already observed in normal tissue of tumor patients compared to healthy donors for THBS2, SPARC, LTBP2 as well as the collagens COL8A1 and COL12A1." (PMID 29176937, 2017). "However, we have illustrated in the present study that intraperitoneal injected SPARC induces activation of Akt and WNK signaling pathways in tumor nodules." (PMID 28969021, 2017). "In addition, macrophage-derived cathepsins, SPARC, or CCL18 enhances the tumour cell adhesion to extracellular matrix proteins and promotes tumour cell migration." (PMID 28210073, 2017). "It showed that elevated expression of SPARC was found in the early stage (I/II) and early tumor infiltration (T1/T2) as well as in patients without lymph node metastasis." (PMID 29156791, 2017). "In bulk tumor‐derived expression data, we found a very strong correlation of SPOCK1 expression with markers of activated stroma: secreted protein acidic and cysteine rich (SPARC), α‐smooth muscle actin (αSMA/ACTA2), and fibroblast activation protein." (PMID 28486750, 2017). "We next established subcutaneous tumor xenografts using KCNR cells mixed with either shSHEP cells (SPARC-negative) or control vcSHEP cells (SPARC-positive) at a 1:4 ratio." (PMID 27776337, 2016). "The results of this analysis demonstrated no expression of SPARC in the tumor transplants generated from the As#6, and Cd#4 cell lines stably transfected with the SPARC open reading frame, whereas Cd#1 exhibitied trace focal expression." (PMID 26783756, 2016). "Tumor generated from the other 3 (As#6, Cd#1 and Cd#7) SPARC-transfected cell lines showed no focal expression of SPARC." (PMID 26783756, 2016). "One of the subgroups was stratified according to cytoplasmic SPARC protein levels (positive [IRS of 6-12] vs negative [IRS 0-5]) in tumor tissues." (PMID 27421134, 2016). "The mechanism linking a surplus of SPARC to cell invasion, however, is not clear due to the challenge of examining SPARCs function in complex tumor environments." (PMID 26926673, 2016). "Another which considered SPARC in the stroma, but not in the tumor was related to better outcome was also reported." (PMID 26731428, 2016). "These rare cells that do not express SPARC, or a subset thereof, are presumably the cells comprising the population of TICs that initiated the tumor transplants." (PMID 26783756, 2016). "Stromal (host) SPARC regulates ECM deposition and modulates tumor growth and progression." (PMID 27564266, 2016). "The effect of SPARC expression on time to recurrence and OS was also not statistically significant when evaluated using a multivariate analysis including age, sex, tumor site, tumor histology, and chemotherapy regimen." (PMID 27544129, 2016). "Urospheres from both the non-transfected and SPARC-transfected cell lines were tumorigenic and thus fit the definition for a population of tumor initiating cells." (PMID 26783756, 2016). "The results demonstrated that the urospheres isolated from the As+3-and Cd+2-transformed UROtsa cell lines not transfected with SPARC were able to form a subcutaneous tumor when transplanted into immune compromised mice." (PMID 26783756, 2016).
tumor (continued). "In contrast, the measured area of the blood vessels in the SPARC-negative tumor xenografts comprised of KCNR and shSHEP cells was similar to the level observed in xenografts established with KCNR cells alone." (PMID 27776337, 2016). "The focal expression of SPARC in the tumor transplants was in agreement with the finding that SPARC mRNA was expressed in these tumors; however, western blotting did not detect the SPARC protein." (PMID 26783756, 2016). "However, after 1–2 cycles of chemotherapy, patients who had PLN involvement at surgery showed significant up-regulation of tumor THBS1, TNC, FN, SPARC and α-SMA expression." (PMID 27487140, 2016). "SPARC was highly expressed in GC compared with the desmoplastic stroma surrounding tumor cells and noncancerous tissues." (PMID 25859409, 2015). "The lowest plasma levels of SPARC were those of SPARC negative primary tumours (n = 3), that showed 5% of cases with faint SPARC staining (representative images for Patient 4)." (PMID 26703564, 2015). "Moreover, implantation of the PEM inhibited tumor-stromal interaction-related expression of proteins such as CD44, SPARC, matrix metalloproteinase-2, and vimentin." (PMID 25983747, 2015). "Suppression of endogenous SPARC expression in both PDAC2 and PDAC3 cell lines using two independent shRNA constructs did not affect proliferation in 2D cultures or anchorage-independent tumor sphere formation." (PMID 25242334, 2014). "Few experimental models have simultaneously addressed the role of both cancerous and non-cancerous SPARC in tumor progression." (PMID 25331979, 2014). "A TRAMP mouse model crossed to SPARC-/- mice concluded that both cancerous and non-cancerous SPARC exert tumor suppressor functions." (PMID 25331979, 2014). "Our above results suggest that expression and secretion of high levels of SPARC by a non-CSC neoplastic cell subpopulation promote the metastatic spread of tumor cells with CSC traits." (PMID 25331979, 2014). "Previous research suggests that SPARC may induce tumor cells to produce MMPs that degrade the ECM, thereby increasing tumor invasion and migration." (PMID 23516489, 2013). "The SPARC and MMP9 are known to interact to regulate many stages of tumor progression." (PMID 23935929, 2013). "SPARC is transcriptionally silenced in AML with rearrangement of the MLL (Mixed lineage leukemia) gene and may function as a tumor suppressor in this subset of patients." (PMID 23383963, 2013). "We provide evidence that the aberrant activation of TGFβ1 in the tumor microenvironment lacking stromal-derived SPARC contributes significantly to the phenotypic alterations observed during progression of orthotopic Pan02 tumors." (PMID 22348081, 2012). "SPARC binds to several types of collagen, including collagen I and III, which are the major structural proteins of the ECM produced by host cells in response to the subcutaneously injected tumor cells." (PMID 22481923, 2012). "Although losartan was able to effectively reduce the expression, activation and signaling of TGFβ1, further validation is needed to prove that it is through the inhibition of TGFβ1 and not angiotensin II that tumor progression is reduced in SPARC−/− mice." (PMID 22348081, 2012). "Neither upregulating SPARC in U87 cells nor suppressing SPARC in LN443 cells had any effect on tumor cell survival after radiation therapy." (PMID 22480225, 2012). "In this study we investigated SPARC and FOXP3 in stage II and III CRC tissue and compare their prognostic value against the known CRC prognostic markers CD8 and CD45RO that are expressed by tumour infiltrating T lymphocytes." (PMID 21818290, 2011). "Stage II CRC patients without disease recurrence, had significantly higher SPARC levels in their primary tumours at all time points up to 60 months, and for most points up to 138 months, compared to those patients suffering a disease recurrence." (PMID 21818290, 2011).
tumor (continued). "In fact, our results demonstrate that tumor xenografts of cells over-expressing only the N-terminus domain of SPARC, and not others, experienced the most dramatic tumor regression in response to chemotherapy." (PMID 22069448, 2011). "Patients whose tumors stoma was positive versus negative for SPARC had median OS of 15 versus 30months (p < 0.001); the same was not seen when comparing tumor cell SPARC." (PMID 22016635, 2011). "Endogenous SPARC inhibits the malignant phenotype of PDAC cells and may, therefore, act as a tumour suppressor in PDAC." (PMID 19920824, 2010). "The cytopathic effect (CPE) of the two CRAds was compared on a panel of tumor cells that expressed or not SPARC mRNA." (PMID 19337591, 2009). "In addition, Runx2 has the potential to regulate the transcription of extracellular matrix modulators such as SPARC and MMP1, thereby influencing the tumour microenvironment." (PMID 17876328, 2007). "High levels of SPARC are not required for tumor progression but are necessary for tumor growth and maintenance." (PMID 17022822, 2006). "Real-time Q-RT–PCR data for the expression of SPARC were measured by the ratio of SPARC signal in tumour tissue to that in noncancerous adjacent tissues." (PMID 15558074, 2004). "Importantly, the expression of SPARC in peritumoral fibroblasts within the stroma is a predictor of poor prognosis for PC patients, whereas SPARC derived from tumor cells does not have prognostic significance." (PMID 40619414, 2025). "Other cancer antigens, while exhibiting downregulated expression in liver tissue compared to primary tumors, may not exhibit as marked a decline as FOXM1 and SPARC, underscoring their distinct biological roles in tumor progression and metastasis." (PMID 40806530, 2025). "In tumor tissues lacking SPARC, the tumor growth rate and volume were significantly reduced." (PMID 37577749, 2023). "The expression of SPARC is not affected by secretions from tumor cells." (PMID 37958984, 2023). "Thus, the super-resolved SPARC-expression image highlighted the potential tumor-invasion region and made it easier to identify by a non-pathologist in cases where a given transcript’s function is known." (PMID 35260632, 2022). "In addition, SPARC expression in tumor stromal cells is a potential negative predictor of paclitaxel treatment in patients with lung cancer." (PMID 35595817, 2022). "However, SPARC and TPM1 roles in tumor-infiltrating require further investigation." (PMID 35477379, 2022). "At the same time, SPARC can also bind to platelet-derived growth factor PDGF to indirectly inhibit angiogenesis by downregulating matrix metalloproteinases (MMPs) and transforming growth factor β1 antibodies (TGF-β1), which in turn inhibits tumor invasion and metastasis." (PMID 35211625, 2022). "Meanwhile, it has been shown that the incidence of SPARC methylation in HCC tissue is much higher than that in non-tumor tissues and that patients without SPARC methylation have a higher postoperative overall survival (OS) rate than patients with SPARC methylation." (PMID 35981080, 2022). "SPARC deletion promoted ROS generation and increased the production of pro-inflammatory and pro-angiogenic cytokines IL-6, CCL2, VEGF, and TNF-α as well as cytokines with pro-migratory ability, CCL3, CXCL2, CSF-1, and M-CSF, accompanied by greater tumor infiltration by mac1-positive TAMs." (PMID 34209679, 2021). "Consistent with the idea that stromal SPARC expression may promote cancer progression, SPARC knockdown in fibroblasts decreased ECM fiber formation and alignment in our study, and these factors play a large role in tumor progression." (PMID 33534863, 2021). "However, the oncogenic roles of SPARC fragments generated by proteolysis in the tumor microenvironment of TNBC were not known." (PMID 33995652, 2021).
tumor (continued). "Moreover, recent data has suggested that specific tumour delivery of nab-paclitaxel is not directly related to SPARC expression, and nab-paclitaxel does not usually deplete tumour stroma." (PMID 34336679, 2021). "Furthermore, SPARC, COL6A3, and FBN1 play an important role in tumor-related immune infiltration and may be ideal targets for immune therapy against PDAC." (PMID 32934754, 2020). "As the in vitro environment is somewhat different to the in vivo tumor environment, SPARC-mediated HSA accumulation may not be as dominant in vitro." (PMID 33114661, 2020). "Therefore, we hypothesized that the overexpressed SPARC M2 conditioned medium may reduce the activation of the AKT/ mTOR pathway in tumour cells, thereby attenuating the M2-mediated malignant tumour phenotype." (PMID 32226513, 2020). "Notably, human BC samples in which SPARC was absent on tumor cells were also devoid of CD33+ cells expressing SPARC, in parallel with mouse results." (PMID 31281314, 2019). "To determine the effect of SPARC on the three TFs in OvCa-adipocytes interactions in vivo, we first determined the levels of total and phosphorylated proteins in lysates of syngeneic ID8 omental tumours that developed after ip injection in SP–/– and SP+/+ mice." (PMID 30765860, 2019). "SPARC is a marker able to identify lesions potentially or actually invasive that are otherwise histomorphologically benign and for which there is no invasive tumour/brain interface available for pathological assessment." (PMID 31123490, 2019). "Only 16/99 specimen had SPARC-positive tumor epithelium while the vast majority was negative." (PMID 31554208, 2019). "SPARC transcript was not correlated with patients’ survival, most probably due to the distinctive compartmentalization of SPARC protein expression in patients’ tumours." (PMID 30765860, 2019). "Importantly, we found significant negative correlation between tumour SPARC with nuclear expression of the p65RelA, cJun, and cEBPβ in advanced stage (T3+) OvCa specimens in TMAs where only tumour cores are present." (PMID 30765860, 2019). "SPARC found in pancreatic stromal tissue correlated with OS but not SPARC derived from tumor cells." (PMID 29623263, 2018). "The expression of SPARC in tumor cells did not significantly affect prognosis." (PMID 29623263, 2018). "In addition, the tumor endothelium expresses two albumin-binding proteins SPARC and gp60 receptor, which may facilitate the uptake and retention of the HSA complex in the tumor interstitium." (PMID 29350051, 2018). "TAMs can also promote tumor cell migration and invasion through the secretion of MMPs, secreted protein acidic and rich in cysteine (SPARC) and cathepsins which degrade and remodel the ECM as well as through the secretion of TGF-β which promotes EMT of tumor cells and increased tumor cell migration." (PMID 30356656, 2018). "The author proposed that the cancer cells might require host SPARC to leave the primary tumor but not to seed to distant organs." (PMID 28969021, 2017). "The finding that the urospheres from the SPARC transfected cells had a very low expression of SPARC mRNA could explain the lack of SPARC expression in the tumor transplants generated from the SPARC-transfected As+3-and Cd+2-transformed cell lines." (PMID 26783756, 2016). "By contrast, SPARC expression on the surface of tumor cells was not predictive of a response." (PMID 27411683, 2016). "However, SPARC expression on the tumor cell surface alone failed to predict response to treatment (74 % [29/39] vs. 59 % [13/22]; OR 1.4; 95 % CI, 0.7–2.8; P = 0.38)." (PMID 27411683, 2016). "We also identified six UPRs unique to CPA-treated B16F10 tumors vs. GL261(B6) tumors that promote tumor cell survival or tissue repair and may contribute to B16F10 tumor unresponsiveness: activated UPRs KDM5B, RBL2 and SPARC; and inhibited UPRs FOXM1, CD24 and CSF2)." (PMID 27515027, 2016).